DEFB110 (defensin beta 110)
Description:
Has antibacterial activity.
Synonyms: DEFB-10; DEFB-11; DEFB111
Tractability: Antibody: UniProt places it where antibodies can reach, with medium confidence; UniProt predicts a signal peptide or a membrane-spanning region; its Gene Ontology location is reachable by antibodies, with medium confidence.
Gene: Protein-coding gene on chromosome 6 (50,009,138 to 50,021,994, reverse strand). Ensembl gene ENSG00000203970.
Subcellular location: Secreted
Pathways (Reactome):
Immune System: Beta defensins; Defensins
Gene Ontology:
Molecular function: CCR6 chemokine receptor binding; chemoattractant activity
Biological process: cell chemotaxis; defense response to bacterium; innate immune response; positive chemotaxis
Cellular component: extracellular region
Genetic constraint (gnomAD): Loss-of-function variants: 8 observed, 4.68 expected, observed/expected ratio (o/e) 1.71, 90% interval 0.91 to 1.95. That is too few expected variants to judge how well the gene tolerates losing a copy. Missense variants: 94 observed, 73.37 expected, observed/expected ratio (o/e) 1.28, 90% interval 1.08 to 1.52. Synonymous variants: 29 observed, 22.32 expected, observed/expected ratio (o/e) 1.3, 90% interval 0.97 to 1.75.
Homologues: Orthologues: chimpanzee DEFB110 (94% identical), macaque DEFB110 (91% identical), dog DEFB110 (78% identical), pig DEFB110 (76% identical), rabbit DEFB110 (72% identical), guinea pig DEFB110 (69% identical), rat Defb17 (69% identical), mouse Defb41 (67% identical).
Diseases named in the same sentence as DEFB110 in open-access papers:
DEFB110 is named in the same sentence as 6 diseases in open-access papers, as found by Europe PMC text mining. Sharing a sentence is not in itself a finding about the gene and the disease.
small cell lung carcinoma (1 paper, 2022). Small cell lung cancer (SCLC) is a highly aggressive malignant neoplasm, accounting for 10-15% of lung cancer cases, characterized byrapid growth, and early metastasis.
DEFB110 also shares sentences with these, for which no sentence is quoted: infection (5 papers); fungal infections (1); male infertility (1); ovarian adenocarcinoma (1); squamous cell carcinoma (1).